PPFIA2 (PPFI scaffold protein A2)
Description:
Alters PTPRF cellular localization and induces PTPRF clustering. May regulate the disassembly of focal adhesions. May localize receptor-like tyrosine phosphatases type 2A at specific sites on the plasma membrane, possibly regulating their interaction with the extracellular environment and their association with substrates. In neuronal cells, is a scaffolding protein in the dendritic spines which acts as immobile postsynaptic post able to recruit KIF1A-driven dense core vesicles to dendritic spines.
Tractability: Antibody: UniProt places it where antibodies can reach, with high confidence. PROTAC: ubiquitination databases record sites on it; its protein half-life has been measured.
Gene: Protein-coding gene on chromosome 12 (81,257,975 to 81,759,553, reverse strand). Ensembl gene ENSG00000139220.
Subcellular location: Cytoplasm; Cell surface; Cell projection, dendritic spine
Pathways (Reactome):
Neuronal System: Acetylcholine Neurotransmitter Release Cycle; Dopamine Neurotransmitter Release Cycle; Glutamate Neurotransmitter Release Cycle; Norepinephrine Neurotransmitter Release Cycle; Receptor-type tyrosine-protein phosphatases; Serotonin Neurotransmitter Release Cycle
Gene Ontology:
Molecular function: protein binding; structural constituent of postsynaptic density; structural constituent of presynapse
Biological process: dense core granule cytoskeletal transport; regulation of dendritic spine development; regulation of dendritic spine morphogenesis; cell-matrix adhesion; synapse organization; maintenance of postsynaptic density structure; presynapse organization; regulation of synaptic vesicle exocytosis
Cellular component: dendritic spine; extracellular exosome; cytoplasm; cytosol; presynaptic active zone; axon; cell surface; glutamatergic synapse; postsynaptic density; postsynaptic specialization; presynaptic membrane; synaptic vesicle
Genetic constraint (gnomAD): Loss-of-function variants: 31 observed, 115.55 expected, observed/expected ratio (o/e) 0.27, 90% interval 0.2 to 0.36. The upper end of that interval is the gene's LOEUF score, 0.36, which puts it in group 1 of 6, group 1 being the genes least tolerant of losing a copy. Missense variants: 935 observed, 1,243.5 expected, observed/expected ratio (o/e) 0.75, 90% interval 0.71 to 0.79. Synonymous variants: 475 observed, 426 expected, observed/expected ratio (o/e) 1.12, 90% interval 1.03 to 1.2.
Homologues: Orthologues: chimpanzee PPFIA2 (99% identical), macaque PPFIA2 (99% identical), rat Ppfia2 (99% identical), mouse Ppfia2 (99% identical), dog PPFIA2 (98% identical), rabbit PPFIA2 (97% identical), pig PPFIA2 (97% identical), tropical clawed frog ppfia2 (92% identical), guinea pig PPFIA2 (89% identical), zebrafish ppfia2 (85% identical), Drosophila melanogaster Liprin-alpha (49% identical). Paralogues in human: PPFIA4 (67% identical), PPFIA1 (67% identical), PPFIA3 (59% identical), PPFIBP1 (18% identical), PPFIBP2 (17% identical).
Diseases named in the same sentence as PPFIA2 in open-access papers:
PPFIA2 is named in the same sentence as 6 diseases in open-access papers, as found by Europe PMC text mining. Sharing a sentence is not in itself a finding about the gene and the disease. The quoted sentences say what the papers report.
liposarcoma (1 paper, 2024). A usually painless malignant tumor that arises from adipose tissue. "In a study trying to find NTRK fusion in solid tumors, one retroperitoneal liposarcoma showed double NTRK3 fusions (MORF4L1:NTRK3 and PPFIA2:NTRK3)." (PMID 39839837, 2024).
myopia (1 paper, 2021). "The involvement of PPFIA2 in the progression of myopia has also received considerable attention." (PMID 34094943, 2021).
cancer (2 papers, 2023 to 2025). A tumor composed of atypical neoplastic, often pleomorphic cells that invade other tissues. "SOD3, HYOU1, and PPFIA2 show the strongest association with both racial differences and survival, indicating a potential role in racial disparities in cancer outcomes." (PMID 40558258, 2025). "Materials and methods: In this study, several databases, including Oncomine, UALCAN, and the cancer cell line encyclopedia, were used to compare differences in PPFIA1, PPFIA2, PPFIA3, and PPFIA4 expression between normal colon samples and CRCs." (PMID 36605492, 2023).
intestinal disorder (1 paper, 2024). A non-neoplastic or neoplastic disorder that affects the small or large intestine. "For instance, Faecalibacterium prausnitzii, which is known for its abundance in the healthy human microbiota and depletion in various intestinal disorders, including CRC, was associated with the methylation of PPFIA2, NR3C1, and EXO1." (PMID 38840170, 2024).
PPFIA2 also shares sentences with these, for which no sentence is quoted: autism (1 paper); neurodevelopmental disorder (1).